E2F1 (E2F transcription factor 1)
Diseases named in the same sentence as E2F1 in open-access papers (continued):
Sharing a sentence is not in itself a finding about the gene and the disease.
seminoma (1 paper, 2024). A radiosensitive malignant germ cell tumor found in the testis (especially undescended), and extragonadal sites (anterior mediastinum and pineal gland). "In this study, we demonstrated that the p73, a target gene of E2F1 related to apoptosis, is involved in the responsiveness of seminoma cells to cisplatin, and its expression is regulated by LINC03074." (PMID 39097584, 2024).
silicosis (1 paper, 2021). Silicosis is a respiratory disease caused by breathing in (inhaling) silica dust. "The current study demonstrated that miR‐205‐5p was poorly expressed in mice with silicosis, which was negatively correlated with the E2F1 expression pattern." (PMID 34428336, 2021). "RT‐qPCR analysis revealed a significantly increased E2F1 expression pattern in silicosis, which was highly positively correlated with the expression pattern of SKP2." (PMID 34428336, 2021). "As shown by IHC, E2F1‐positive cells were increased notably in the alveolar tissues of mice with silicosis." (PMID 34428336, 2021). "Decreased Beclin1 and increased SKP2 and E2F1 were identified in mice with silicosis." (PMID 34428336, 2021). "Moreover, the mice with silicosis following treatment of miR‐205‐5p agomir showed upregulated expression patterns of Col1a1, Col3a1 and LC3, while this upregulation was annulled by Lenti‐E2F1, Lenti‐SKP2 or siBeclin1." (PMID 34428336, 2021).
steatosis (1 paper, 2021). Increased lipid within the cytoplasm of cells. "E2F1 deletion can completely abrogate hepatic steatosis in different murine models." (PMID 33868403, 2021).
subarachnoid haemorrhage (1 paper, 2017). "Interestingly, the loss of GCN5 activity and the induction of Egr-1, E2F1 and Bim are involved in the early brain injury (EBI) following subarachnoid haemorrhage (SAH) in rats." (PMID 28125090, 2017).
synovial sarcoma (1 paper, 2023). "This suggests a transcriptional regulation of ETV5 on E2F1, but in an opposite direction than the one established in the synovial sarcoma report." (PMID 37876309, 2023).
teratocarcinoma (1 paper, 2013). A germ cell tumor characterized by the presence of an embryonal carcinoma component and a teratoma component. "They reported that human stem cells and teratocarcinoma cells show a selective reduction in the expression of E2F1, E2F2, E2F3 and p105 (encoded by NFKB1) and enhanced expression of E2F4, E2F5, E2F6 and p130 (encoded by RBL2) compared with human normal somatic IMR90 cells." (PMID 24355041, 2013).
thymoma (1 paper, 2011). A neoplasm arising from the epithelial cells of the thymus. "Similarly, mice deficient for E2F1 were predisposed to thymomas due to their inability to delete t cells via E2F1-mediated apoptosis." (PMID 22272113, 2011).
uterine cancer (1 paper, 2023). Primary or metastatic malignant neoplasm involving the uterine corpus and/or the cervix. "In addition, E2F1 is reported to be involved in uterine cancer progression." (PMID 37175660, 2023).
Wilms tumor (1 paper, 2008). An embryonal neoplasm characterized by the presence of epithelial, mesenchymal, and blastema components. "Important for their relation to Wilm's Tumor, several of these TFs have previously been implicated in cancer (NANOG, GLI1, E2F1, POU5F1/OCT4, SPI-1, YY-1, GATA1, and C/EBP-β)." (PMID 18564415, 2008).
ZIKV infection (1 paper, 2017). "One recent study reported that several apoptotic regulators, including ZMAT3, PMAIP1, TNFRSF10D, BBC3, were upregulated, and cell cycle genes, such as E2F1 and E2F2, were downregulated after ZIKV infection." (PMID 29116029, 2017).
tumor (859 papers, 2002 to 2026). "For example, circCAMSAP1 is implicated in tumor progression by sponging miR-328-5p, a tumor-suppressor miRNA, which typically represses the oncogenic transcription factor E2F1." (PMID 40724932, 2025). "This study provides new insights by confirming the causal relationship between high E2F1 expression and enhanced tumor stemness through both mechanistic experiments and clinical validation." (PMID 40886002, 2025). "The tumor sphere formation assay suggested that E2F1 deficiency decreased the sphere formation rate in Huh-7 and Hep3B cells." (PMID 40221814, 2025). "In vivo assay, E2F1 deficiency suppressed HCC tumor growth and eliminated cancer stemness, while these effects were abolished by EXOSC10 up-regulation." (PMID 40221814, 2025). "Drives steatosis, lipotoxicity, cell apoptosis, and tumor cell survival in hypoxic environments; linked to genetic mutations (e.g., E2F1/E2F2 activation)." (PMID 41262444, 2025). "In TNBC, E2F1 is particularly implicated in promoting aggressive tumor characteristics through the upregulation of CCNA2, which regulates both the G1/S and the G2/M transition phases, and POLD2, which is crucial for DNA replication and repair." (PMID 41413688, 2025). "Since E2F1-deficient mice developed a wide range of malignancies, the E2F member E2F1 was characterised as a tumour suppressor." (PMID 38792263, 2024). "used a bitransgenic mouse model of Myc-induced T cell lymphomagenesis and analyzed tumor progression in mice deficient for E2F1, E2F2, or E2F3." (PMID 38807594, 2024). "In contrast, E2F1 contributes to tumor suppression by activating tumor suppressor genes, such as ARF, upon loss of pRB function, a major oncogenic change." (PMID 39595534, 2024). "In vivo assays also showed that forced expression of E2F1 reversed the suppression of tumor growth and metastasis induced by NSUN2 deficiency." (PMID 38424195, 2024). "E2F1, a pivotal transcription factor for cell cycle governance, is linked to tumor progression when aberrantly expressed, and has a supportive role in advancing GC, amplifying the ability of cancer cells to grow and spread." (PMID 39172101, 2024). "A good example for cooperativity associated with changes in the tumor immune contexture is the complex between E2F1 and metastasis-associated protein 1 (MTA1)." (PMID 39544930, 2024). "Since expression of PSMD14 is associated with tumor promotion through interaction with the transcription factor E2F1, our results further support that PSMD14 plays a role in cancer progression of HNSCC." (PMID 35750900, 2023). "In fact, previous studies have found that E2F1 expression was elevated in tumor tissues and associated with the poor prognosis of cancer." (PMID 37277745, 2023). "On the other hand, further studies on different tumor entities showed an association between E2F-1 and resistance to chemotherapy." (PMID 37719017, 2023). "E2F1 plays a dual role in tumor growth, where rising E2F1 can either cause apoptosis or stimulate tumor development and invasion." (PMID 37569304, 2023). "Previous studies also uncovered high burden of E2F1 CNVs which drive tumor susceptibility in many caner types." (PMID 37497116, 2023). "E2F1 has been implicated in multiple biological processes and in tumorigenesis, leading potentially to both tumor-promoting as well as tumor-suppressive effects." (PMID 37705754, 2023). "Dissociation of this pro-metastatic circuit by targeting E2F1:MTA1 assembly reduced tumor-associated macrophage infiltration in the TME." (PMID 36678712, 2022). "E2F1 was first identified as a protein that belongs to the E2F family, which is known for binding to the retinoblastoma protein (pRB), a tumor inhibitor mutated in many types of cancer." (PMID 36284303, 2022). "Cross comparison of our DEGs to a E2F1 cistrome revealed many E2F1 target genes (E2f7, Rtel1, Myc, Ybx3 and Id3) being downregulated in β1 integrin-deficient tumours, consistent with slow tumour growth phenotype." (PMID 34782719, 2022).
tumor (continued). "Tumor type-specific gene signatures were detected, showing that highly expressed E2F1 in combination with TGFBR1, and FGFR1 is causatively implicated in EMT-driven invasiveness." (PMID 36678712, 2022). "In CRC, previous studies have reported 35-37 that elevated E2F1 expression exhibits an inverse association with cell proliferation and a positive correlation with increased apoptotic levels, suggesting a tumor-suppressive role in CRC progression." (PMID 35069909, 2022). "It is well known that E2F1 was associated with enhanced tumour cell apoptosis or proliferation depending on cell lines and mouse models." (PMID 35448958, 2022). "The transcription factor E2F1 and pathways linked to tumor stemness are highly activated in baseline biopsies from patients whose tumors undergo lineage plasticity." (PMID 36109521, 2022). "Retrospective studies of several cancers, including NSCLC, indicate that an upregulated E2F1 expression is frequently associated with high-grade tumours and a poor patient survival prognosis." (PMID 33883577, 2021). "Except for one PyMT E2F1 knockout tumor, the rate of exonic SNVs ranged from 0.005 to 0.08 mutations per megabase." (PMID 33947907, 2021). "The association between E2F1 expression level and the risk of tumor relapse two years after surgery was also analyzed." (PMID 33986804, 2021). "In vivo experiments showed that the intratumoral injection of M/T-Exo caused greater tamoxifen resistance and larger tumor size relative to mice treated with miRNA-205-knockdown or E2F1-overexpressing BCCs." (PMID 34292880, 2021). "Rb is often mutated and E2F1 activity increased in tumour cells, making these aspects relevant considerations for MDM2 inhibition therapy." (PMID 34911439, 2021). "In vivo recovery of E2F1 expression levels also rescued the tumour proliferation inhibition caused by CDCA8 knockdown." (PMID 34741389, 2021). "In our HCC cohort, the genetic locus 20q11.2, which encodes E2F1, was recurrently amplified in tumours, E2F1 expression was moderately and strongly upregulated in GE1-HCC and GE2-HCC, respectively." (PMID 33541355, 2021). "The more complex tumor‐promoting effects of ARRB1 loss are related to the protein's importance for inducing E2F1 acetylation, a modification that ultimately leads to the transcriptional activation of E2F1's pro‐apoptotic target genes." (PMID 32920979, 2021). "E2F1 serves as a predictor of tumor recurrence risk in male GC patients within two years after surgery." (PMID 33986804, 2021). "Other studies demonstrated that increased E2F1 expression was significantly associated with favorable prognosis and tumor stage." (PMID 34499617, 2021). "Given the short latency of PyMT mice, it was surprising to observe tumor latency in PyMT mice significantly decreased with E2F1 loss while growth rate remained unaffected." (PMID 33947907, 2021). "It has been demonstrated in RCC that the loss of VHL gene function leads to the accumulation of E2F1, which promotes cell senescence and thus inhibits tumor progression." (PMID 34499617, 2021). "E2F1 was found to be a risk factor for tumor relapse in all GC patients (both male and female), even though the difference was not significant (p=0.067)." (PMID 33986804, 2021). "The transcription factor E2F1 has also been highlighted as a tumor-associated gene based on its role in the cell cycle pathway, with targets of E2F1 reported to play an important role in the progression of LSCC13." (PMID 34408262, 2021). "Multiple mutational profiles can be associated with a particular etiology, even though the mutational profiles themselves are distinct from each other.Together, these data suggest E2F1 loss drives differences in DNA repair and tumor etiology." (PMID 33947907, 2021).
tumor (continued). "In TIMER datasets, the E2F1 expression in GBM showed a positive association with tumor purity while the E2F1 expression in LGG demonstrated a very weak interrelation with CD8+ T cells infiltration level." (PMID 33381564, 2020). "Increased E2F1 expression has been reported to be associated with cell migration and tumor development." (PMID 31936744, 2020). "The mRNA expression levels of E2F1/3/5/8 were found to be significantly upregulated in patients with OC and were obviously associated with tumor stage for OC." (PMID 30967995, 2019). "Deregulation of E2F1-pRB binding increases the access of E2F1 to E2F1-binding target genes, containing the E2F-binding site, and this is thought to increase the susceptibility of tumor development." (PMID 31338064, 2019). "Many studies have documented E2F1 overexpression in various human cancers causing tumor progression, invasion and metastases." (PMID 30279956, 2018). "Previous studies have demonstrated a tight association between downregulation of specific miRNAs and E2F1 overexpression in tumor tissues." (PMID 28704519, 2017). "E2F1 has been found to be involved in tumor suppression and cell cycle, and the loss of E2F1 results in the progress of carcinogenesis and the decrease of lymphocyte tolerance." (PMID 28302063, 2017). "E2F1 gene expression was similar between normal and tumor tissues bearing the germline alteration; however, expression was increased 4-fold in tumor tissue that harbored a somatic mutation compared to that in normal tissue." (PMID 28704519, 2017). "E2F1 was the first member of the E2F family to be identified because of its ability to bind the retinoblastoma protein (pRB), a tumor suppressor mutated in many types of cancer." (PMID 29176962, 2017). "The E2F member E2F1 induces target gene transcription during the G1 to S transition, and is defined as a tumor suppressor because the E2F1-deficient mice developed a wide variety of cancers." (PMID 29263891, 2016). "E2F transcription factor 1 (E2F1) is another transcription factor that influences apoptotic susceptibility of tumor cells by regulating alternative splicing of apoptotic genes." (PMID 27613060, 2016). "We investigated associations of E2F1 and TS expression with the following parameters: age and gender of patients, tumor grade, stage, and tumor site." (PMID 26831819, 2016). "E2F1 promotes cellular proliferation pathways as loss of E2F1 inhibits tumor development in tumor prone mice heterozygous for RB1." (PMID 26670255, 2015). "A genetic cross of MMTV-Neu mice into an E2F1 null, E2F2 null, or E2F3 heterozygous background revealed significant changes in tumor progression specifically reductions in tumor latency and metastasis with E2F1 or E2F2 loss." (PMID 26682278, 2015). "E2F1 similarly functioned as a tumor suppressor in HPV-positive oral tumors as tumors grew faster with homozygous loss of E2F1 compared to tumors with heterozygous loss of E2F1." (PMID 26670255, 2015). "In Rb;p107-deficient retinae, E2f1 and E2f3 inactivation rescued tumor formation but only E2f1 rescued the retinal development phenotype." (PMID 25338120, 2014). "Elevated E2F1 expression was associated with larger tumor size, advanced pT stage and higher TNM stage." (PMID 24023875, 2013).
tumor (continued). "Although initially considered as a potential oncogene due to its ability to drive S-phase progression in quiescent cells, data obtained in E2F1-null mice revealed a potential tumor suppressor role associated with impaired apoptosis induction." (PMID 24381932, 2013). "Further analysis in 92 cases indicated that E2F1 mRNA level expression was associated with the tumor pathologic parameters embracing diameter, Fuhrman tumor grade, pT stage, TNM stage grouping and macrovascular infiltration (MAVI)." (PMID 24023875, 2013). "As we have previously reported, this treatment regimen markedly prolongs survival of tumor-bearing mice and is associated with reduced E2F1 and FASN expression and with diminished proliferation in the tumors, as indicated by reduced levels of cyclin D2." (PMID 22407012, 2012). "We have performed the first exome sequencing of a WDPMP tumor and a matched control sample and a tumor-derived cell line and discovered the first somatic mutation of E2F1, R166H." (PMID 21955916, 2011). "The mutant's stability and large quantities will favor its preferential binding to Rb due to its sheer numbers and the heterozygous nature of the mutation in the WDPMP tumor would ensure active copies of wild-type E2F1 were present to drive the cell cycle." (PMID 21955916, 2011). "Earlier studies with E2F1 reported that overexpression of E2F1 in tissue culture cells and in transgenic mice caused a stimulation of apoptosis and an enhancement of tumour formation." (PMID 22272113, 2011). "E2F1 deregulation is a common feature among different tumor types and can be a major cause of cell proliferation." (PMID 21637599, 2010). "Among the significant genes that show a high expression in tumours with unfavourable outcome, cell cycle associated genes can be found (E2F1, CCNA2, CCNB1, KIFC1)." (PMID 17531100, 2007). "Thus, the ability to modulate E2F1 transcription network with minimal cytotoxicity holds promise for improving the clinical management of EBV-associated neoplasms." (PMID 40773523, 2025). "Notably, KI-AA1524/CIP2A also interacts with several phosphorylated PP2A substrates involved in tumor growth, including c-Myc, polo-like kinase 1 (Plk1), E2F1, Akt, and death-associated protein kinase 1 (DAPK1)." (PMID 41154660, 2025). "Thus, it is important to elucidate the regulatory mechanism of deregulated E2F1 activity in order to understand the molecular basis of tumor suppression that antagonizes the loss of pRB function." (PMID 39595534, 2024). "Furthermore, a significant association was found between the E2F1 rs3213180 polymorphism and tumor size (T) (p = 0.039), lymph node involvement (N) (p = 0.005), and LSCC clinical stage (ST) (p = 0.008)." (PMID 38360622, 2024). "In fact, the balance in the TME involves more than one cytokine, which could be achieved by directly silencing tumor-associated E2F1." (PMID 39544930, 2024). "The inactivation of RB1 leads to the activation of E2F1, causing tumor cell proliferation." (PMID 37781033, 2023). "Additionally, we discovered that tumor-associated transcription factors E2F-1 regulate MAD2L2 expression by directly binding to its promoter region." (PMID 38017538, 2023). "POH1 was also found to reverse K63- and K11-linked polyubiquitination of E2F1 for tumor formation." (PMID 35100873, 2022). "However, in addition to the role of E2F1 in tumor defense mechanisms, there is evidence to date that E2F1 mediates pathological cell death that causes tissue destruction (e.g., neuronal degeneration and ischemic cell damage)." (PMID 35457270, 2022). "The results demonstrate that E2F1 is up-regulated in GC and associates with tumor malignancy and poor prognosis, suggesting that E2F1 may play a key role in GC tumorigenesis." (PMID 35440106, 2022). "Tumor-related studies have shown that the upregulation of factor E2F1 can cause pathological pain." (PMID 33494823, 2021).